RNU6-436P (RNA, U6 small nuclear 436, pseudogene)
Gene: Small nuclear RNA gene on chromosome 2 (157,912,772 to 157,912,885, forward strand). Ensembl gene ENSG00000251980.
Homologues: Orthologues: macaque U6 (95% identical), chimpanzee U6 (89% identical). Paralogues in human: RNU6-854P (68% identical), RNU6-73P (67% identical), RNU6-737P (66% identical), RNU6-1152P (65% identical), RNU6-209P (65% identical), RNU6-211P (65% identical), RNU6-301P (65% identical), RNU6-552P (65% identical), RNU6-647P (65% identical), RNU6-1087P (64% identical), RNU6-1124P (64% identical), RNU6-1145P (64% identical), and 1284 more.